INMT (indolethylamine N-methyltransferase)
Diseases named in the same sentence as INMT in open-access papers (continued):
Sharing a sentence is not in itself a finding about the gene and the disease.
pulmonary fibrosis (1 paper, 2025). Chronic progressive interstitial lung disorder characterized by the replacement of the lung tissue by connective tissue, leading to progressive dyspnea, respiratory failure, or right heart failure. "The first markers of pulmonary fibrosis were detected at 48 hours including indolethylamine N-methyltransferase and nestin." (PMID 40665229, 2025).
Salmonella Infections (1 paper, 2021). Infections with bacteria of the genus SALMONELLA. "We also identified some new host proteins that have never been reported in Salmonella infection previously, such as indolethylamine N-methyltransferase (INMT) and peroxisomal trans-2-enoyl-CoA reductase (PECR)." (PMID 34461813, 2021).
cancer (11 papers, 2012 to 2025). A tumor composed of atypical neoplastic, often pleomorphic cells that invade other tissues. "According to several studies, dysregulated INMT expression has been implicated in the development and progression of several human cancers." (PMID 41008295, 2025). "Dysregulation of INMT activity has been linked to a range of pathological conditions, including neuropsychiatric disorders, neurodegeneration, and several forms of cancer." (PMID 41008295, 2025). "Collectively, the diverse tissue distribution of INMT provides a mechanistic rationale for its emerging associations with neuropsychiatric disorders, cancer, and neurodegeneration, which will be discussed in the following section." (PMID 41008295, 2025). "This indicates the potential for INMT to serve as a valuable diagnostic and prognostic biomarker for various cancers." (PMID 41008295, 2025). "One proposed mechanism linking low INMT expression to prognosis is that the INMT enzyme has a role in detoxifying various cancer cells, particularly by methylating biogenic monoamines possessing mitogenic activity, such as serotonin, tryptamine, and tyramine." (PMID 41008295, 2025). "We found that the mRNA expression of INMT was significantly lower in cancer cells than in LO2 hepatocytes." (PMID 37202783, 2023). "INMT mRNA expression was significantly lower in multiple human cancers, specifically in HNSC, in comparison with their respective normal tissues." (PMID 36186458, 2022). "The study of the molecular mechanism of INMT would help us better understand the process of tumorigenesis and development and find new targets in cancers." (PMID 36437916, 2022). "As a result of pan-cancer analysis, we also discovered that different expressions of INMT were observed in various types of tumors." (PMID 36186458, 2022). "CRHR2, INMT, and GALNT9 expression have been shown to be associated with cancer and may play a role in regulating the self-renewal and proliferation of cancer stem cells." (PMID 40358182, 2025). "The observed pattern suggested that INMT plays a role in cancer development and may impact tumor progression, cell proliferation, and the tumor microenvironment." (PMID 41008295, 2025). "However, our results are only analyzed based on the public data, and further molecular experiments on cancer cell lines are needed to explore the mechanism of INMT in tumorigenesis and the development of LUAD." (PMID 36437916, 2022). "Evidence suggests that the expression of INMT is reduced in several cancers." (PMID 36186458, 2022). "Deregulation of INMT expression in primary cancer of lung and prostate has been reported, however, the role of INMT in cancer is unknown." (PMID 34587977, 2021). "However, the INMT’s exact role and the molecular mechanism in cancer and other disorders remain unclear." (PMID 41008295, 2025). "Furthermore, targeting INMT may potentially offer an alternative therapeutic strategy for a range of illnesses, such as cancer, psychiatric disorders, and neurodegenerative diseases." (PMID 41008295, 2025). "This suggests that low expression of INMT may be a common phenomenon in cancer cells." (PMID 35252179, 2022). "INMT promotes CRPC growth and development via methylation and detoxification of the anticancer metabolites that are produced in cancer cells and/or released from tumor microenvironment." (PMID 34587977, 2021). "Using pan-cancer analysis, we found that the different expression of INMT between cancer and adjacent non-malignant tissues was widespread in several tumors." (PMID 35252179, 2022). "As N-methylation of endogenous and xenobiotic compounds leads to the degradation of the compounds, INMT may promote CRPC growth and development by detoxification of the anticancer metabolites that are produced in cancer cells and/or existed in tumor microenvironment." (PMID 34587977, 2021).
tumor (11 papers, 2021 to 2025). "Our study revealed that INMT is closely linked to the tumor microenvironment, as an enzyme crucial to tryptophan metabolism." (PMID 36186458, 2022). "We found that INMT, as a critical enzyme in tryptophan metabolism, is closely associated with the tumor microenvironment." (PMID 35252179, 2022). "Using pathway analysis, we found that, in addition to tryptophan metabolism and selenocompound metabolism, INMT was involved in many tumor signaling pathways, including the MAPK, TGFβ, and Wnt signaling pathways." (PMID 35252179, 2022). "Tumor lymphocyte infiltration in HNSC is related to INMT expression and methylation, respectively (TISIDB)." (PMID 36186458, 2022). "We found that knockdown of INMT significantly decreased Myc-CaP allograft tumor development in mouse models." (PMID 34587977, 2021). "Based on the basic structures of the known substrates of INMT, we designed the experimental procedures for analyzing and comparing the potential substrates of INMT in tumor tissues." (PMID 34587977, 2021). "We also found that INMT-KD DU145 cells grew tumor much slower than control cells in Rag1−/− male mice." (PMID 34587977, 2021). "These context-specific patterns suggest a complex, tumor-type-dependent role for INMT." (PMID 41008295, 2025). "The literature also indicates that TPTE, INMT, and STAR are differentially expressed in tumours and may be associated with prognosis." (PMID 36818393, 2023). "The expression of INMT is down-regulated in many tumorous tissues, and it may contribute to tumor invasion and metastasis." (PMID 36186458, 2022). "All these studies revealed that the lower expression of INMT may promote tumour progression." (PMID 37202783, 2023). "As both KEGG and GO enrichment analyses illustrated that INMT may be involved in the tumor immune response, employing the TIMER, we first investigated the association between INMT expression and the six types of tumor-infiltrating immune cells." (PMID 36186458, 2022). "Compared to adjacent normal tissues, tumor tissues exhibited significantly reduced expression of PTGIS, DGKB, HSD17B13, INMT, and ACACB, while PLA2G10, GRHL1, LIPG, and PLA2G4F were markedly upregulated." (PMID 40426878, 2025). "Hence, these findings strongly demonstrate that the INMT gene might contribute to tumor immunity." (PMID 36186458, 2022). "The high expression of INMT mRNA and protein in CRPC tumor tissues and in purified tumor cells was further examined and confirmed by real-time PCR, western blot analysis and immunohistochemistry." (PMID 34587977, 2021). "Our results showed that PYCR1, INMT, and KIF20A were significantly upregulated in tumor cells." (PMID 41013841, 2025). "It is worth noting that overexpression of INMT in Myc-CaP cells did not increase the proliferation of Myc-CaP cells cultured in charcoal-treated medium and Myc-CaP allograft tumor development in castrated FVB male mice." (PMID 34587977, 2021).
Bacterial infections (1 paper, 2021). "Pathway analysis revealed multiple related functions of the new features, such as Viral mRNA Translation (INMT), GABA receptor binding (GABARAP), Bacterial infections in CF airways (TOLLIP), signaling (RALGDS) and others." (PMID 34302024, 2021).
neurodegenerative disease (1 paper, 2025). A disorder of the central nervous system characterized by gradual and progressive loss of neural tissue and neurologic function. "The co-localization of INMT with S1R in the motoneurons might explain the possible role of INMT in neuroprotection, signaling function, and disease pathology; nevertheless, the exact molecular mechanism associating INMT with neurodegenerative diseases remains unclear." (PMID 41008295, 2025).
INMT also shares sentences with these, for which no sentence is quoted: non-small cell lung carcinoma (3 papers); adenocarcinoma (1); arrhythmogenic right ventricular cardiomyopathy (1); bladder urothelial carcinoma (1); breast invasive carcinoma (1); colon adenocarcinoma (1); colorectal cancer (1); dilated cardiomyopathy (1); endocervical adenocarcinoma (1); Fanconi anemia (1); glioma (1); Hypertension (1); hypertrophic cardiomyopathy (1); infection (1); lymph node metastasis (1); Obesity (1).